RN7SL208P (RNA, 7SL, cytoplasmic 208, pseudogene)
Gene: Miscellaneous RNA gene on chromosome 5 (76,836,900 to 76,837,195, reverse strand). Ensembl gene ENSG00000264391.
Homologues: Orthologues: chimpanzee Metazoa_SRP (99% identical), macaque Metazoa_SRP (92% identical), rabbit Metazoa_SRP (59% identical). Paralogues in human: RN7SL1 (81% identical), RN7SL126P (80% identical), RN7SL2 (80% identical), RN7SL3 (80% identical), RN7SL597P (79% identical), RN7SL481P (78% identical), RN7SL147P (78% identical), RN7SL448P (77% identical), RN7SL507P (77% identical), RN7SL652P (77% identical), RN7SL664P (77% identical), RN7SL828P (77% identical), and 704 more.